HIF1A (hypoxia inducible factor 1 subunit alpha)
Diseases named in the same sentence as HIF1A in open-access papers (continued):
Sharing a sentence is not in itself a finding about the gene and the disease.
breast cancer (continued). "In response to hypoxic conditions, cancer cells adapt to the stress environment by upregulating a transcription factor called hypoxia-inducible factor-1α (HIF-1α), which plays a critical role in the growth, invasion, metastasis, and therapeutic resistance of breast cancer." (PMID 36080483, 2022). "There was a positive correlation between HCG18 and HIF-1α expression in breast cancer tissues." (PMID 36139678, 2022). "Moreover, transfection of miR-340-5p mimics can significantly inhibited the expression of SIAH2 and HIF-1α in breast cancer SP cells exposed to hypoxia." (PMID 35309179, 2022). "Higher HIF-1α abundance is also a common feature of breast cancers, due not only to the lack of oxygen but also to mutations in oncogenes or tumor suppressor genes." (PMID 36057753, 2022). "The functional interaction between Erα and HIF-1α transduction pathways in breast cancer has been corroborated by evidence showing that HIF-1α may confer resistance to ER antagonists and may be considered as a transcriptional target of Erα." (PMID 35158804, 2022). "Importantly, AXL was recently shown to be required to generate the hypoxic response in HER2+ breast cancer by regulating HIF-1α expression." (PMID 35158733, 2022). "Moreover, Nrf2 has a key role in the activation of HIF1α, which is followed by enhanced glycolysis, which enhances breast cancer progression." (PMID 35571115, 2022). "In addition, STAT3 was reported to be activated by inflammatory cytokines, such as IL6, IL8 and TNFα, which enhance breast cancer proliferation, invasion and metastasis through the upregulation of Twist, Snail, Slug, Vimentin and HIF-1α." (PMID 35747796, 2022). "However, the rate of positivity in the studies that examined HIF-1α in breast cancer ranges from 1% to 80.2%, probably due to the use of different cutoff points and assessment systems." (PMID 36358811, 2022). "To test whether HIF-1α inhibition can confer an immunotherapeutic effect in a non–breast cancer model, we repeated the experiments using MC38 murine colon adenocarcinoma cells." (PMID 35239514, 2022). "Results of the study on breast cancer cell lines suggest the need to consider aspects like HIF-1α versus HIF-2α inhibition, double versus singular isoform inhibition, different hormone receptors status, metastases, and perhaps different not yet investigated issues." (PMID 36139678, 2022). "In the case of glioma, breast cancer, and prostate cancer, HIF-1α activates pro-survival pathways such as Notch, wingless, INT-1 (WNT), and the Hedgehog pathway, which are important for CSC maintenance, which leads to radioresistance and repopulate CSCs during or after treatment." (PMID 36014432, 2022). "In conclusion, this study confirmed that YTHDF1 is overexpressed in breast cancer and associated with poor prognosis, while hypoxia can promote the expression of YTHDF1 by inducing HIF1α at transcriptional level and inhibiting endogenous miR-16-5p expression at post-transcriptional level." (PMID 35319018, 2022). "TAMs promote aerobic glycolysis in breast cancer via HIF‐1α‐stabilizing long noncoding RNA (HISLA)." (PMID 34914196, 2022). "Thus, we assessed the impact of 1 on HIF-1α protein expression using MDA-MB-231 breast cancer cells." (PMID 36296726, 2022). "Therefore, sinomenine can inhibit hypoxia-mediated EMT process of breast cancer SP cells by repressing the SIAH2/HIF-1α axis." (PMID 35309179, 2022). "Furthermore, hypoxia results in increased expression of plasminogen activator urokinase receptor (PLAUR) via HIF-1α expression in breast cancer." (PMID 36140753, 2022). "RBC numbers found in the lung parenchyma were lower in 40-week-old mice compared to 20-week-old mice suggesting impaired pulmonary capillary perfusion and were consistent with higher HIF1α levels in 40-week-old mice compared to 20-week-old mice after the injection of 4T1 breast cancer cells." (PMID 36504711, 2022).
breast cancer (continued). "In breast cancer, HIF-1α protein is a marker of poor prognosis and disease progression." (PMID 35140341, 2022). "In addition, results showed that HNK-mediated HIF-1α degradation was required for inhibitory effect of HNK on colony formation of breast cancer cells." (PMID 35350760, 2022). "Furthermore, the novel circRNF20 (hsa_circ_0087784) is expressed at high levels in breast cancer (BC), and promotes the proliferation and glycolysis of BC cells via the miR-487a/HIF-1α/HK2 axis." (PMID 35915091, 2022). "However, the proportional relevance of these genes varies by cell type; for example, HIF-1α is mostly responsible for the response to hypoxia in the endothelium and breast cancer cells, but HIF-2α is responsible in renal carcinoma cells." (PMID 35592530, 2022). "Taken together, we suggest that HIF-1α signaling is vital in ATP-driven chemoresistance and may serve as a potential target for breast cancer therapies." (PMID 35236823, 2022). "Furthermore, breast cancer patients expressing high levels of HIF-1α suffer from poorer disease-free survival (DFS) as well as worse overall survival (OS)." (PMID 35413842, 2022). "HIF-1α/VEGF-A axis is an important pathway for T cells to adapt to the hypoxia microenvironment Analysis of human breast cancer showed that VEGF-A expression was negatively correlated with CD8+ T cell infiltration, and there was a relationship between T cell infiltration and vascular formation." (PMID 36226050, 2022). "In addition, Chang found that in breast cancer, HIF-1α promotes EZH2 transcription and upregulates EZH2 expression by binding to HRE in the EZH2 promoter region." (PMID 35779185, 2022). "Because HNK can inhibit glycolysis mediated by HIF-1α and the growth of cancer cells, we constructed a nude mouse model of breast cancer transplantation to observe whether HNK can inhibit glycolysis mediated by HIF-1α and slow down tumor growth in vivo." (PMID 35350760, 2022). "Thus, it was proposed that metabolic rewiring by elevated levels of DKG led to stabilization of HIF-1α and reprogramming of breast cancer cells into a stem-like state." (PMID 36497394, 2022). "HIF-1α has been reported as a prerequisite for chemotherapy resistance (paclitaxel and gemcitabine) of breast cancer stem cells by inducing ROS-dependent expression of HIF-1α and HIF-2α, leading to HIF-mediated expression of IL-6, IL-8, and MDR1, thereby promoting the survival of BCSCs." (PMID 36003773, 2022). "HIF-1α can induce the expression of ALDH1A1 in breast cancer cells under hypoxic conditions." (PMID 36139678, 2022). "In addition, after the transcriptional activation by HIF-1α in breast cancer (BC), BCRT acts as a miRNA sponge to inhibit miR-1303." (PMID 35625948, 2022). "In addition, it was reported that OL inhibits the migration through suppression of EMT in breast cancer cells, and it also inhibits the proliferation of colorectal cancer cell through downregulation of HIF-1α signal." (PMID 36050634, 2022). "Overexpressed circPVT1 enhances the migration of breast cancer cells by overexpressing HIF1A." (PMID 36230902, 2022). "Therefore, the inhibition of mTOR not only has a therapeutic effect but also reduces HIF-1α expression in breast cancer." (PMID 35413842, 2022). "In addition, the expression of key glycolysis genes GLUT1, HK2 and PDK1 was detected in breast cancer cells overexpressing HIF-1α after HNK treatment." (PMID 35350760, 2022). "Moreover, there is a feedback loop that allows C/EBPδ to amplify IL-6 and HIF-1α expression, as was observed in a breast cancer model." (PMID 35565420, 2022). "Immunohistochemistry of 45 patients of breast cancer showed that high levels of HIF1α were positively correlated with increased microvascular density (a measure of angiogenesis) (P=0.023) and with expression of angiogenic growth factors bFGF and PDGF-BB and receptor EGFR." (PMID 36226050, 2022).
breast cancer (continued). "The association between primary tumour HIF-1α positivity and IBTR is, to our knowledge, a novel finding, and in line with previous reports that hypoxia and HIF-1α are associated with distant metastasis and poor prognosis in breast cancer." (PMID 35140341, 2022). "This is a significant finding since HIF-1α is a direct target of ERα in breast cancer cells, suggesting that estrogen-activated hypoxia signaling could also contribute to muscle fibrosis." (PMID 35439171, 2022). "Aminoflavone, aromatic hydrocarbon receptor ligands, effectively inhibit expression of HIF1A mRNA in breast cancer cells and almost completely block accumulation of the HIF1A protein as well as transcription of downstream target genes in an aromatic hydrocarbon receptor-independent manner." (PMID 35659268, 2022). "Similarly, LC3B puncta were also observed in the hypoxic regions of MMTV-pyMT mouse breast cancer tissue characterized by HIF-1α in the nucleus." (PMID 35436985, 2022). "The interaction between PAD4 and HIF-1α has been shown to promote breast cancer angiogenesis and tumor growth in animal models and breast cancer patients, suggesting that PAD4 inhibition may be a novel treatment strategy for TNBC." (PMID 36365233, 2022). "Moreover, miR-100 and miR-16 shuttled by BMMSC-EVs suppressed breast cancer cells angiogenesis in vitro through modulating the mTOR/HIF-1α/VEGF signaling axis, suppressed angiogenesis by down-regulating VEGF expression in breast cancer cells, respectively." (PMID 35915054, 2022). "Furthermore, exposure to hypoxia increases the number of breast cancer stem cells (CSCs), and in agreement, inhibiting HIF-1α leads to tumor regression and delays tumor recurrence." (PMID 35158815, 2022). "Also, in murine transgenic breast cancer models, it has been shown that TAMs exert an HIF-1α dependent immunosuppressive effect triggering a hypoxia-induced suppression of T-cell functions." (PMID 34539584, 2021). "In breast cancer, tanshinone I downregulates hypoxia-inducible factor 1alpha (HIF-1α) and VEGF in breast cancer MDA-MB-231 cells, and tanshinone IIA inhibits the angiogenesis and growth of human breast cancer xenografts in nude mice through suppression of HIF-1α and VEGF." (PMID 35145409, 2021). "The data showed that CoCl2 promotes HIF-1α expression in both breast cancer cells." (PMID 34055597, 2021). "Future studies may be strengthened by examination of HIF-1α expression in premenopausal breast cancer patients and conservation of HIF-1α expression in tumors over time." (PMID 34736510, 2021). "The data indicated that HIF-1α was a direct downstream gene of miR-7641 in breast cancer cells." (PMID 34238918, 2021). "Furthermore, inhibition of HIF-1α was reported to improve the efficacy of a DC-based vaccine in 4T1 breast cancer model." (PMID 34202979, 2021). "Hypoxia significantly increased the expression of Hif-1α in breast cancer cells." (PMID 35011574, 2021). "UCA1 is one of the HIF-1α-regulated lncRNAs in hypoxic breast cancer." (PMID 34054950, 2021). "cCr may be an effective anti-metastatic agent in ER-negative, HIF-1α-positive breast cancers, targeting both cellular metabolism and motility, particularly when paired with conventional cytotoxic agents." (PMID 35008190, 2021). "Additionally, several studies discuss the role of various therapeutic agents targeting diabetes and breast cancer, while also implicating HIF1-α." (PMID 34225729, 2021). "This is consistent with the known role of HIF1A in breast cancer." (PMID 33502086, 2021). "However, other studies suggest that HIF‐1α induces the metabolic reprogramming of CAFs and increases glycolysis, thereby promoting tumour growth in breast cancer." (PMID 33943003, 2021).
breast cancer (continued). "A recent meta-analysis, which included 14 studies, reported that high HIF-1α expression among breast cancer patients was an indicator of poor prognosis, and was associated with both overall survival (hazard ratio [HR] = 1.46, 95%CI 1.12, 1.92) and disease-free survival (HR = 1.91, 95%CI 1.43, 2.57)." (PMID 34736510, 2021). "Interestingly, lungL2 had the greatest upregulation in HIF1A, a known marker of hypoxia and poor prognosis in breast cancer." (PMID 34579762, 2021). "Considering that the high expression of HIF-1α has been related to resistance to radiotherapy and chemotherapy in breast cancer, we next investigated the role of JFK in breast cancer cell sensitivity to ionizing radiation (IR) and chemotherapeutic agents under hypoxia." (PMID 34336836, 2021). "Hence, to date, to the best of our knowledge, there has been very limited prior experimental study designed to potentiate the role of HIF1-α in diabetes-breast cancer crosstalk." (PMID 34225729, 2021). "Thus, HIF1α can directly activate CUL4B expression by binding to the hypoxia hormone response element (HRE) on the CUL4B promoter in breast cancer cells." (PMID 34026424, 2021). "Furthermore, clinical evidence from breast cancer patients shows that high HIF1α levels in primary tumors correlate with poor patient outcomes, and a hypoxic transcriptomic signature in tumor cells is associated with bone metastasis." (PMID 34556788, 2021). "Thus, we aimed to investigate how CBD can interfere with HIF-1α signaling, followed by inhibition of the proliferation and angiogenesis of breast cancer." (PMID 34830821, 2021). "Hypoxia-inducible factor-1α (HIF-1α) is a transcription factor that facilitates the adaptation of cancer cells to hypoxic conditions and may be prognostic of breast cancer recurrence." (PMID 34736510, 2021). "Therefore, both digoxin and acriflavine are suitable candidates for clinical trials for breast cancer, especially in those patients whose primary tumours express high levels of HIF-1α." (PMID 35006432, 2021). "In addition, AMPK is known to potentiate doxorubicin resistance in breast cancer, and HIF-1α can be stabilized by AMPKα2, one of the catalytic subunits of AMPK." (PMID 34575983, 2021). "Nrf2 overexpression can induce the activation of glucose-6-phosphate dehydrogenase (G6PD)/HIF-1α signaling, consequently conferring the proliferation and metastasis of breast cancer cells via EMT signaling (epithelial–mesenchymal transition) due to extensive NADPH levels." (PMID 33466626, 2021). "Similarly, the expression of HIF-1α was also activated when fibroblasts were induced to CAFs after co-culture with breast cancer cells in previous studies." (PMID 34631221, 2021). "A two-phases response is observed in prostate cancer (PC) and breast cancer cells, as well as in osteosarcoma exposed to 1% O2 tension: after an initial up-regulation of HIF-1α, the protein is gradually reduced notwithstanding the persistence of hypoxic conditions." (PMID 33423689, 2021). "Additionally, a combination treatment involving polydatin and 2-deoxy-d-glucose in breast cancer induced apoptosis by targeting ROS/PI3K/AKT/HIF-1α/HK2." (PMID 34577602, 2021). "Therefore, CBD can attenuate Src/VHL/HIF-1α signaling and inhibit angiogenesis, followed by inhibiting the growth and invasion of breast cancer and cancer stem-like properties." (PMID 34830821, 2021). "Interestingly, another study showed that hypoxia-induced lincRNA-P21 promoted the Warburg effect to increase ATP generation by regulating HIF-1α transcriptional activity in breast cancer." (PMID 34977036, 2021). "Nrf2 also regulates aerobic glycolysis via HIF-1α in breast cancer." (PMID 34772403, 2021). "Together these findings support our hypothesis that the HIF-1α-JFK axis contributes to breast cancer cell survival." (PMID 34336836, 2021).
breast cancer (continued). "In breast cancer, HIF-1α transcriptionally activates the expression of genes with known functions in cell survival, angiogenesis, metabolic reprogramming, invasion, and metastasis, through binding to hypoxia response elements (HREs) in the promoters of its target genes." (PMID 34336836, 2021). "However, the role of HIF-1α in the regulation of UCA1 in breast cancer has rarely been investigated." (PMID 34054950, 2021). "Furthermore, bone metastases are more frequently formed by breast cancer cells with an expression of the hypoxia-inducible factor 1α (HIF-1α), a transcription factor responding to hypoxic conditions." (PMID 34064589, 2021). "One of a mechanism of miR-7641 in suppressing cancer stemness might down-regulate HIF-1α expression in breast cancer cells." (PMID 34238918, 2021). "Moreover, HS-1793 can exert potent anti-breast cancer effects via hindering HIF-1α-mediated transcriptional activation of VEGF expression in vitro and in vivo." (PMID 34575983, 2021). "Moreover, TNF-α was reported to increase the proportion of breast cancer stem-like cells through NF-κB/HIF1α/Slug, indicative of primary breast tumors with self-renewal capacities that are resistant to cell death." (PMID 33816268, 2021). "While targeted inhibition of HIF1α or HIF2α could be beneficial in preventing bone metastasis, HIF1α inhibition may promote the outgrowth of lung-disseminated breast cancer cells." (PMID 34556788, 2021). "In breast cancer, patients with disseminated tumor cells in the bone marrow tend to express higher levels of HIF1α in their primary tumors, suggesting that HIF1α signaling may promote tumor dissemination to the bone marrow." (PMID 33919988, 2021). "Pharmacological inhibition or knockdown of HIF‐1α expression sensitizes resistant breast cancer cells to TAM and other endocrine‐therapy agents, which suggests that HIF‐1α may be a promising target for the treatment of TAM‐resistant breast cancer." (PMID 34841716, 2021). "Although miR-210 has been proven to be a target of HIF-1α in breast cancer cells, whether HIF-1α regulates miR-210 transcription in CAFs has not yet been reported." (PMID 34631221, 2021). "HIF1α expression in breast cancer cells promotes bone colonization and osteolysis following intracardiac or orthotopic inoculation of MDA-MB-231 human breast cancer cells, and hypoxic transcriptomic signatures in breast cancer cells has been associated with bone metastasis." (PMID 34556788, 2021). "Here, we asked whether TIMP-1-induced HIF1α results in increased CAIX expression in our breast cancer progression model." (PMID 34685701, 2021). "In addition, HIF-1α-stabilizing long non-coding RNA (HISLA) is transferred from TAMs to breast cancer cells via extracurricular vessel transmission, which increases glycolysis in breast cancer cells." (PMID 34552932, 2021). "However, the putative anti-tumoral CBD effect on angiogenesis through HIF-1α signaling in breast cancer or BCSCs is poorly understood." (PMID 34830821, 2021). "HIF1α is hyperactivated and participates in promoting breast cancer progression." (PMID 34686682, 2021). "In this study, we did not observe an association between HIF-1α expression and breast cancer recurrence or timing of breast cancer recurrence among women in the ER+/TAM+ stratum." (PMID 34736510, 2021). "HIF-1α has emerged as a LRRK2 phosphorylation target in normoxia in human breast cancer cells." (PMID 34439955, 2021). "In the ER+/TAM+ stratum, we observed a near-null association in the odds of breast cancer recurrence among women with tumors positive for HIF-1α expression compared with those without HIF-1α expression (OR = 1.21, 95% CI: 0.88, 1.67)." (PMID 34736510, 2021). "Our exploratory analyses suggested that breast cancer patients in the ER−/TAM− group who had positive HIF-1α expression in their primary and recurrent tumors were more likely to have had early recurrence (< 5 years), although the small sample size yielded imprecise results." (PMID 34736510, 2021).